GATA3 (GATA binding protein 3)
Diseases named in the same sentence as GATA3 in open-access papers (continued):
Sharing a sentence is not in itself a finding about the gene and the disease.
hypoparathyroidism (continued). "Haploinsufficiency of GATA3 causes Hypoparathyroidism, Deafness and Renal dysplasia (HDR) syndrome." (PMID 34033651, 2021). "Therefore, only GATA3 heterozygous mutations that cause a haploinsufficiency of GATA3 in the hypoparathyroidism, deafness, and renal dysplasia (HDR) patients have been reported." (PMID 33126494, 2020). "In humans, the expression of GATA3 is localized to the cochlear duct and the spiral ganglion between weeks 8 and 12 of gestation; the loss of GATA3 in inner hair cells leads to hearing loss and accounts for some of the deafness connected to hypoparathyroidism and renal anomaly (HDR) syndrome." (PMID 34426786, 2021). "In addition, the slightly decreased 1,25‐(OH)2D of the proband which should be lower due to the hypoparathyroidism caused by the mutation of the GATA3 gene, and the increased 1,25‐(OH)2D of his father, reinforce our hypothesis." (PMID 32155322, 2020). "Similarly, both Gata3 which causes hypoparathyroidism, sensorineural deafness, renal anomaly (HDR) syndrome with uterine hypoplasia and Fgfr2, which causes disorders of sexual dimorphism in males, and decidualization defects in females, are highly expressed in the inhibited MISR2+ progenitors." (PMID 31232694, 2019). "HDR (hypoparathyroidism, sensorineural deafness, renal dysplasia) syndrome, which is characterized by a variety of craniofacial defects, is an autosomal dominant condition caused by mutations in the gene encoding a human zinc finger transcription factor, GATA3." (PMID 23720234, 2013). "Hypoparathyroidism, sensorineural deafness, and renal dysplasia (HDR) syndrome is a rare autosomal dominant disorder caused by pathogenic variants in the GATA3 gene." (PMID 42017099, 2026). "Deletions involving a critical region containing the GATA3 gene on chromosome 10p lead to hypoparathyroidism, sensorineural deafness, and renal insufficiency syndrome (HDRS)." (PMID 40869914, 2025). "Hypoparathyroidism, sensorineural deafness, and renal dysplasia (HDR) syndrome is caused by pathogenic variants in the GATA3 gene located on chromosome 10p14." (PMID 41190486, 2025). "In the proband’s sister, we found a p.Trp329Gly missense in GATA3, the gene responsible for the rare syndrome “hypoparathyroidism, sensorineural deafness, and renal dysplasia” (HDR)." (PMID 39062799, 2024). "GATA3 mutations are known to cause HDR syndrome, characterized by hypoparathyroidism, deafness and renal dysplasia." (PMID 35990004, 2022). "GATA3 haploinsufficiency participates in the pathogenesis of the hypoparathyroidism, sensorineural deafness and renal dysplasia (HDR) syndrome." (PMID 36002896, 2022). "Haploid GATA3 deficiency leads to a clinical triad represented by Hypoparathyroidism, Deafness, and Renal anomaly (HDR syndrome), underscoring the essential function of GATA3 in development of these tissues." (PMID 33803938, 2021). "Hypoparathyroidism, deafness, and renal dysplasia (HDR; OMIM 146255) syndrome is a rare disease, inherited dominantly and found to be related with GATA3 (GATA binding protein 3) gene mutations." (PMID 26777049, 2015). "Previous studies have shown that pathogenic point variants (SNVs) in the GATA3 gene do not cause facial dysmorphism, which is considered a differentiating feature in the genetic diagnosis of congenital hypoparathyroidism." (PMID 40686918, 2025). "Hypoparathyroidism, deafness, and renal dysplasia (HDR) syndrome is an infrequent autosomal dominant genetic disorder caused by haploinsufficiency of the GATA binding protein 3 (GATA3) gene." (PMID 37693317, 2023). "GATA3 is associated with HDR syndrome, i.e., hypoparathyroidism, SN deafness and renal dysplasia." (PMID 34440452, 2021).
hypoparathyroidism (continued). "Hypoparathyroidism, sensorineural hearing loss, and renal disease (HDR) syndrome, also known as Barakat syndrome, is a rare genetic disorder with high phenotypic heterogeneity caused by haploinsufficiency of the GATA3 gene on chromosome 10p14-p15." (PMID 29073906, 2017). "In patient 4, the phenotype could be explained by the deletion of two genes: GATA3 (hypoparathyroidism, sensorineural deafness, and renal insufficiency) and AKR1C4 (46,XY sex reversal)." (PMID 25435912, 2014). "Therefore, all the phenotypes presented in our patient (including sensorineural deafness, renal anomalies hypoparathyroidism, hypocalcemia, and hyperphosphatemia induced by hypoparathyroidism), could be explained by GATA3 defect except for the hypercalciuria." (PMID 32155322, 2020). "While the Guardant360 test is not intended to report germline mutations, we set a VAF cutoff of 40% to identify potential germline GATA3 alterations, which result in HDR syndrome (hypoparathyroidism, deafness, renal dysfunction)." (PMID 40439821, 2025). "Greater than 90% of AIRE mutation-negative probands with suspected familial hypoparathyroidism had apparently isolated hypoparathyroidism, and around 30% of these probands were found to have an abnormality affecting either the CASR, GATA3, GCM2, GNA11 genes or the 22q11.2 chromosomal region." (PMID 35521792, 2022).
Allergy (43 papers, 2007 to 2025). An allergy is an immune response or reaction to substances that are usually not harmful. "Chronic elevation of GATA3 is linked to allergies and a less ideal gastrointestinal immune response; however, it is unclear what transient post-prandial elevations, such as those observed in the present study, truly mean." (PMID 39457699, 2024). "Numerous SNPs associated with allergic diseases, autoimmune diseases, and hematopoietic malignancies have been reported near the GATA3 locus." (PMID 38923989, 2024). "For example, GATA3 is known to have a key role in Th2 differentiation in allergy, but is also a potential diagnostic marker in epithelial cancers." (PMID 24571673, 2014). "The recently approved CFTR potentiator, ivacaftor, decreased inflammation in an in vivo mouse allergy model and reduced GATA3 expression and effector function in in vitro polarized human Th2 cells." (PMID 40131363, 2025). "This supports an important role of canine GATA-3+ dn T cells in type 2 immunity, like anti-parasite responses and/or allergy." (PMID 38835756, 2024). "A recent study revealed that GATA3-TSS interacts specifically with the SNP-accumulated region in memory Th2 cells, which suggests the causal involvement of the 10p14 locus in allergic diseases." (PMID 38923989, 2024). "GATA3 is pivotal not only in allergic diseases but also in hematopoietic cell development and several malignancies." (PMID 38923989, 2024). "Incoming Tregs in these settings instead trended for the enrichment of Helios+ (Ikzf2) cells (feeding vs. allergy P = 0.059), which were primarily either Gata3-high in allergy or Gata3-intermediate in tolerance." (PMID 37191720, 2023). "Type 2 immunity consists of GATA3+ Th2 cells and mediates allergy by producing IgE antibody as well as IL-4, IL-5, and IL-13." (PMID 35484967, 2022). "Th2 cells can also be regulated by the transcription factor GATA-3 and secrete IL-4, IL-5, IL-13 and other effector cytokines to regulate allergic reaction." (PMID 33194780, 2020). "Fenugreek extract prevented the differentiation of Th2 cells in splenocytes of mice with allergy, reducing the secretion of IL-4 and expression of GATA-3 mRNA, an IL-4 transcription factor." (PMID 30513929, 2018). "The anti-inflammatory properties of cyclitols and the ability of DP to enhance the expression of the transcription protein GATA-3, the key molecule regulating Th1/Th2 balance, can be used in the treatment of allergic diseases (atopic dermatitis, asthma)." (PMID 30513929, 2018). "Regarding its important regulatory role in Th2 cell differentiation and Th2 cytokine secretion, GATA-3 is considered to be an important target for allergic diseases." (PMID 25187805, 2014). "Recently, we found that rutin inhibits ionomycin/phorbol myristate acetate-induced Th2 signaling and GATA3 to attenuate allergy mediated by the activation of peroxisome proliferator activator receptor-gamma." (PMID 23843865, 2013). "The elevation of GATA3 is a common event in allergic diseases including AA." (PMID 40391221, 2025). "Finally, LP Tomato+ cells from both tolerance and allergy upregulated Gata3, which was primarily expressed in Tregs in this sequencing dataset." (PMID 37191720, 2023). "In addition, we would like to conduct an in vivo study using mycobacterium-infected Th2-biased ovalbumin-challenged or GATA-3 transgenic animals to better dissect the interaction between allergy and Mtb infection in the future." (PMID 34202662, 2021). "In naïve CD4+ T cells, which express a moderate level of GATA3 mRNA after receiving signals via the T cell receptors (TCRs) in the presence of IL-4, activated STAT6 proteins bind to the GATA3 gene locus, driving Th2 differentiation, which is a characteristic in the development of allergy." (PMID 33193294, 2020).
Allergy (continued). "In line with present observations, HDM/DNCB stimulation upregulated the T-bet, STAT3, and GATA3 and other allergy mediating cytokines (IL-4, IL-5, IL-10, IL-13, and IFN-γ) and chemokine (TARC) expression levels, while these were dose-dependently downregulated following SHE treatment." (PMID 32824648, 2020). "Therefore, it is conceivable that canine GATA-3+CD4−CD8α− dn T cells play a role in type 2 immunity such as anti-parasite responses or in the pathophysiology of allergy." (PMID 31824515, 2019). "GATA3 plays a crucial role in the differentiation of Th2 cells and in the development of allergies." (PMID 31826043, 2018). "As GATA-3 is a Th2-specific transcription factor and plays a pivotal role in the allergic immune response, it is considered as an important therapeutic target for treating allergic diseases." (PMID 25187805, 2014). "Prevention of phospho-GATA-3 interaction with importin-α may provide a new approach for the development of novel therapies for the treatment of allergic diseases." (PMID 19436703, 2009). "GATA-3 plays a critical role in regulating the expression of the cytokines interleukin (IL)-4, IL-5, and IL-13 from T helper-2 (Th2) cells and therefore is a key mediator of allergic diseases." (PMID 19436703, 2009). "IL-4 treatment in mice reduces iTreg cell frequency, highlighting that therapeutic approaches that target IL-4 or GATA3 might provide new preventive strategies facilitating tolerance induction particularly in Th2-mediated diseases, such as allergy." (PMID 18162042, 2007). "However, our findings that NK-4 inhibited IL-4 and IL-5 secretion by Th2 cells through down-regulating GATA-3 and NFATc1 mRNA expression suggest that NK-4 could be an effective strategy for the treatment of Th2-mediated allergic disease." (PMID 29933387, 2018). "Finally, these findings suggest that the interaction between phosphorylated GATA-3 and importin-α might be a potential target for new treatments for allergic diseases." (PMID 19436703, 2009). "IL-5 is mainly produced by T helper-2 (Th2) lymphocytes, mainly involved in the response to parasites and allergies, and group 2 innate lymphoid cells (ILC2), and its expression is regulated by several transcription factors, such as GATA3 (BioCarta GATA3 pathway (p-value = 0.009, FDR = 0.099)." (PMID 36835433, 2023). "In allergic diseases, two subpopulations of CD4+ cells play major roles: Th2 cells, which express transcription factor GATA binding protein 3 (GATA3) and induce the production of IgE, and regulatory T cells (Tregs) which are the main inducers of tolerance towards the antigens." (PMID 34394086, 2021). "In line with the protective effects that were observed on acute allergic symptoms and IgE, histone acetylation of Th2-related genes (GATA3, IL-4, IL-5, and IL-13) of splenocyte-derived CD4+ T cells after allergy induction was lower in raw milk-treated mice than in shop milk-treated mice." (PMID 31349704, 2019). "Yet, the central role of such cells is debated because IL-4 production upon re-stimulation has been shown to be restricted to CD4+GATA3+ T cells in patients with known atopy, suggesting that the role of TH2 responses in IgG4-RD might be confounded by concomitant allergic disease." (PMID 28348556, 2017). "At the age of 18 months, the expression of FOXP3, GATA-3, and CTLA-4 in Tregs was higher in the children with allergen-specific IgE sensitization without signs of clinical allergy when compared to the children who did not develop clinical allergies." (PMID 31749800, 2019).
neuroblastoma (43 papers, 2009 to 2025). Neuroblastoma (NB) is the most common solid, extracranial childhood tumor. "In the current study, neuronal differentiation, induced by RA, was accompanied by GATA3 downregulation in neuroblastoma cells, whereas upregulation of GATA3 was associated with increased self-renewal and proliferation of neuroblastoma cells." (PMID 25351211, 2015). "The results demonstrated that GATA3 is a prognostic marker for survival in patients with neuroblastoma, and that high-level GATA3 expression is associated with increased self-renewal and proliferation of neuroblastoma cells." (PMID 25351211, 2015). "Subsequent analysis of clinical relevance revealed that high GATA3 expression tended to be associated with poor prognosis, indicating a close correlation between GATA3 expression levels and the clinical properties of neuroblastomas." (PMID 33803938, 2021). "Therefore, our results identify DNA methylation of GATA3 as a characteristic of the mesenchymal hNCC-like differentiation pathway, with loss of GATA3 methylation in neuroblastoma cell lines and tumours, which contain mainly adrenergic cells." (PMID 31831790, 2019). "The results indicated that GATA3 may be associated with the degree of neuroblastoma differentiation and the consequent prognosis." (PMID 25351211, 2015). "Low expression of GATA3 was associated with a high degree of differentiation, indicating that GATA3 may be of use as a prognostic marker in neuroblastoma." (PMID 25351211, 2015). "In contrast, NIPBL peaks that overlapped with MYCN binding were significantly enriched for motifs recognized by core regulatory circuitry (CRC) transcription factors critical to neuroblastoma cell identity, including GATA3, PHOX2A HAND1, and HAND2." (PMID 40867243, 2025). "The analysis of public ChIP‐seq data confirmed that GATA3 binds to the genomic region containing rs2863002 in 5 different neuroblastoma cell lines." (PMID 40525640, 2025). "Similarly, TFs linked to neural development including MYCN, PHOX2B, SOX10, and GATA3, drive high-risk neuroblastoma (NB)." (PMID 41228232, 2025). "GATA2 has been identified as a component of the transcriptional regulatory circuits involving super enhancers in neuroblastoma cells, which also includes GATA3, PHOX2A, PHOX2B, and HAND2." (PMID 36980710, 2023). "GATA3 has also been shown to be part of the core transcriptional regulatory circuitry in MYCN-amplified neuroblastoma cells and plays an oncogenic role in high-grade serous ovarian carcinoma." (PMID 36856111, 2023). "We also identified cancer-unique vulnerabilities that have been previously reported, such as BRD inhibitors and GATA3 essentiality for neuroblastoma." (PMID 37255415, 2023). "It suggested that the GATA3 transcriptional network was a promising target for novel neuroblastoma therapies." (PMID 35592755, 2022). "GATA3 affects neuroblastoma proliferation by regulating epigenetic transcriptional control networks." (PMID 35592755, 2022). "ChIP-seq for the PHOX2B, HAND2, and GATA3 TFs in the neuroblastoma CLB-GA cell line confirmed that binding regions for these three TFs corresponded to the H3K27ac peaks and SEs of the NOR identity." (PMID 34200747, 2021). "Cyclin D1 maintains cellular proliferation in the vast majority of neuroblastoma tumors, suggesting that GATA3 exerts oncogenic potential by transactivating cyclin D1 in neuroblastomas." (PMID 33803938, 2021). "Identification of direct target genes regulated by GATA2 and/or GATA3 for neuroblastoma proliferation has become increasingly important." (PMID 33803938, 2021). "As anticipated, GATA3 siRNA (small interfering RNA) knockdown in neuroblastoma cell lines inhibited proliferation and increased apoptosis." (PMID 33803938, 2021). "In these neuroblastoma cell lines, the DNA methylation level of the GATA3 gene locus was lower than that in normal human neural crest cells." (PMID 33803938, 2021).